STAT3 (signal transducer and activator of transcription 3)
Diseases named in the same sentence as STAT3 in open-access papers (continued):
Sharing a sentence is not in itself a finding about the gene and the disease.
colorectal cancer (continued). "In summary, our study demonstrates the evident suppressive effects of CWQ against colitis-associated colorectal cancer progression via modulation of microbiota, inflammation resolution and inhibition of STAT3 signalling." (PMID 30905249, 2019). "Numerous reports have implicated the expression of p-STAT3 with lymph node spread as well as the depth of invasion in colorectal cancer." (PMID 30123088, 2018). "For instance, activation of STAT3 by immune cells and cancer-associated fibroblasts had been shown to be essential in colorectal cancer." (PMID 29636641, 2018). "TNF-α, IL-6, NF-κβ, and STAT3 turned out to be associated with intestinal inflammation, leading to a predisposition to colorectal cancer associated with colitis." (PMID 30545135, 2018). "MiR-124 has been shown to post-transcriptionally target signal transducer and activator of transcription 3 (STAT3), which is overly activated in each stage of colorectal cancer development and is associated with tumor-mediated immunosuppression." (PMID 28061475, 2017). "For example, in colorectal carcinoma biopsies STAT3 overexpression has been associated with an improvement in median survival of about 30 months." (PMID 28709401, 2017). "A recent study has reported that persistent activation of Stat3 by the Sphk1/S1P signaling pathway is observed in chronic intestinal inflammation and colitis-associated colorectal cancer." (PMID 27050145, 2016). "Odds ratios (ORs) with 95% CI were combined to evaluate the association between p-STAT3 expression and clinicopathological parameters in patients with colorectal cancer." (PMID 27504822, 2016). "The combined HR and 95% CI demonstrated that p-STAT3 overexpression was significantly associated with poorer overall survival in colorectal cancer patients." (PMID 27504822, 2016). "The meta-analysis results suggest that p-STAT3 overexpression is unfavorable for the prognosis of colorectal cancer patients, and p-STAT3 overexpression is associated with the presence of lymph node metastasis among colorectal cancer patients." (PMID 27504822, 2016). "Hazard ratios (HRs) with 95% confidence intervals (CI) were combined to evaluate the association between p-STAT3 expression and overall survival of colorectal cancer patients." (PMID 27504822, 2016). "Seven studies evaluated the association between p-STAT3 overexpression and overall survival in colorectal cancer patients." (PMID 27504822, 2016). "We found that overexpression of p-STAT3 was significantly associated with the presence of lymph node metastasis in colorectal cancer." (PMID 27504822, 2016). "In the present study, 7 studies including 1528 cases were included to evaluate the association between p-STAT3 expression and overall survival in colorectal cancer patients." (PMID 27504822, 2016). "Recent studies have demonstrated that the Sphk1/S1P axis causes the activation of NF-kB and transcription factor STAT3 and connects chronic inflammation and colitis-associated colorectal cancer, providing a novel mechanism of colitis malignant transformation." (PMID 27050145, 2016). "In conclusion, our meta-analysis demonstrates that overexpression of p-STAT3 has a significant association with poorer overall survival and the presence of lymph node metastases in colorectal cancer patients." (PMID 27504822, 2016). "The activation of IL-6/STAT3 axis has been associated with chemoresistance and poor prognosis of a variety of cancers including colorectal carcinoma and thus serves as a potential immunotherapeutic target for cancer treatment." (PMID 27006530, 2016). "Multiple signaling pathways such as Wnt/β-catenin, MAPK, PI3 K, JAKs/STAT3 and NF-κB signaling pathways are implicated in colorectal cancer development." (PMID 26839513, 2015). "In fact, other studies have demonstrated that the transcription factor STAT3 also plays a critical role in inflammation-associated colorectal cancer formation." (PMID 25166914, 2014).
colorectal cancer (continued). "The role of Stat3 activation in iron-induced colonic inflammation and tumorigenesis was investigated in a mouse model of inflammation-associated colorectal cancer." (PMID 24223168, 2013). "Our findings demonstrate that STAT3 protein expression is significantly higher in colorectal cancer than in normal tissue and is associated with tumor grade." (PMID 23170117, 2012). "Furthermore, the observed sex-specific differences, with enhanced activation of the JAK2/STAT3 axis in male UC patients, shed light on their elevated risk for colorectal cancer development." (PMID 40761789, 2025). "Furthermore, it has been shown that elimination of Stat3 from epithelial cells greatly hinders the development of colitis-associated colorectal cancer." (PMID 38717677, 2024). "Finally, PDIA3 was implicated in the proliferative dynamics of colorectal cancer cells through the STAT3/PD-1 network." (PMID 38761176, 2024). "Blocking the IL-6-STAT3 signaling pathway by CN-encapsulated probiotics prevented the prevention of colitis-associated colorectal cancer was achieved, which further confirmed the pathogenic role of STAT3 in colitis-associated colorectal cancer." (PMID 38717677, 2024). "A study of sporadic colorectal cancer has shown that IL-21 deficiency may be associated with impaired STAT3 and NFκB signaling activity in immune and neoplastic cells." (PMID 35410210, 2022). "The IL-6/STAT3 pathway is associated with an advanced stage in colorectal cancer patients." (PMID 32422984, 2020). "Increases in nuclear STAT5 have been linked to early recurrence and poor survival outcomes in prostate cancer, and overactivation of STAT3 that is associated with decreased survival and high risk of recurrence in renal cell carcinoma, glioblastoma, cervical cancer, colorectal cancer, and melanoma." (PMID 31842362, 2019). "Similarly, in colorectal cancer the loss of lncRNA Casc2 (Cancer susceptibility candidate 2), which normally functions to suppress errant STAT3 signaling by directing PIAS3 expression, has been associated with disease progression." (PMID 31842362, 2019). "Particularly in cancers associated with chronic inflammation such as liver and colorectal cancers, STAT3 activation by growth factors or interleukins suppresses T cell activation and promotes the recruitment of anti-immunity factors such as myeloid-derived suppressor cells and regulatory T cells." (PMID 31684858, 2019). "Consistently, Anxa2 associates with STAT3 and confers the aggressive behavior in colorectal cancer." (PMID 31113450, 2019). "The phenomenon might be associated with autonomous slight STAT3 activation in colorectal cancer cells, which needed to be further investigated." (PMID 29348540, 2018). "Deficiency in STAT3 has been shown to protect against colitis-associated colorectal cancer in mice." (PMID 27006530, 2016). "Furthermore, there was a significant heterogeneity in the analysis of the association between p-STAT3 expression and lymph node metastasis in colorectal cancer." (PMID 27504822, 2016). "However, the association of positive p-STAT3 expression with clinicopathological parameters and the prognosis of colorectal cancer patients remain controversial." (PMID 27504822, 2016). "Relevant to cancers, IL-6 activates STAT3 signaling pathways and high levels of IL-6 is associated with poor prognosis in a variety of cancers such as prostate cancer, bladder cancer, ovarian cancer, colorectal cancer and GC." (PMID 25928408, 2015). "They observed STAT3 could also directly associate with the ZEB1 promoter in colorectal carcinoma cells." (PMID 24743777, 2014).
colorectal cancer (continued). "Persistent STAT3 activation is associated with enhanced proliferation and invasion of colorectal cancer cells in vitro and tumour growth in a colorectal tumour model in vivo, and inhibition of STAT3 induces apoptosis and reduces tumour cell invasion in colorectal cancer cells." (PMID 21694723, 2011). "Additionally, constitutive STAT3 activation in colorectal cancer cells is associated with invasion, survival, and growth of colorectal cancer cells and the colorectal tumor model in mice in vivo." (PMID 20712901, 2010). "Colorectal cancer (CRC) is a serious worldwide health concern associated with chronic inflammation and dysregulation of numerous signaling pathways, including IL-6/STAT3, NF-κB, COX-2/PGE2, and IL-23/Th17." (PMID 41616596, 2026). "Collectively, these findings provide compelling evidence that CDN suppresses colorectal cancer by inhibiting the JAK/STAT3 signaling pathway." (PMID 41585878, 2025). "TNFα plays an important role in increasing the phosphorylation and expression of STAT3 and its target genes related to cell survival and metastasis of colorectal cancer." (PMID 40558596, 2025). "The binding between c‐Met and B7‐H3 was found to be crucial in maintaining the cancer cell stemness of both glioblastoma (GBM)‐ and colorectal cancer (CRC)‐derived tumor cells primarily via the activation of c‐Met/STAT3 signaling pathway." (PMID 40859957, 2025). "SLC9A2 loss enhances colorectal cancer metastasis and immunotherapy resistance by inhibiting STAT3 signaling and angiogenesis, establishing it as a key tumor suppressor and biomarker for colorectal cancer." (PMID 40474298, 2025). "This acid had positive results upon colorectal cancer stem cells through the down-regulation of the JAK2/STAT3 signaling pathway, improved response to 5-fluorouracil treatment, and the decreased viability of cancer cells." (PMID 39859345, 2025). "Studies in colorectal cancer models demonstrate that SPINK1 enhances STAT3 phosphorylation in an IL-6-dependent manner, thereby promoting tumor cell invasion and metastasis." (PMID 40904507, 2025). "PRRX1 upregulation promotes proliferation, stemness, and chemoresistance in colorectal cancer cells by activating the interleukin-6 (IL-6)/JAK2/STAT3 axis, with IL-6 inhibition reversing its effects on stemness and chemoresistance." (PMID 40860778, 2025). "Since STAT3 is considered to be a therapeutic target in colorectal cancer, this would be interesting to further investigate." (PMID 41153795, 2025). "Our results suggest that inhibitors of Nampt can suppress Stat3 expression in colorectal cancer cells via a mechanism mediated by NAD+." (PMID 40492508, 2025). "The presented results indicated that UA promoted apoptosis in colorectal cancer cells through upregulation of miR-4500 and suppression of STAT3 phosphorylation." (PMID 41373772, 2025). "STAT3 is also activated in colorectal cancer (CRC) and promotes tumor growth and progression in conjunction with the IL-6 signaling pathway." (PMID 39995416, 2025). "This crosstalk is amplified by IL-6, which is secreted predominantly by myeloid cells and activates STAT3 and β-catenin nuclear translocation in epithelial cells, fostering colorectal cancer progression." (PMID 40562870, 2025). "Another study focusing on tumor-initiating cells found increased levels of COL17A1 in a STAT-3–dependent manner, which correlated inversely with survival in patients with colorectal cancer." (PMID 40728119, 2025).
colorectal cancer (continued). "Moreover, given the established association between STAT3 activation and an increased risk of developing colorectal cancer due to colitis, the observed increase in STAT3 phosphorylation in males may be linked to the higher incidence of colorectal cancer reported in male UC patients." (PMID 40761789, 2025). "For example, corylin, an isoflavone isolated from Cullen corylifolium (L.)Medik, was found to be able to inhibit colorectal cancer cell proliferation and induce apoptosis by decreasing p-STAT3/STAT3 protein levels." (PMID 41019996, 2025). "It has been shown to stabilize c-Myc via S62 phosphorylation, promote STAT3 and ERK signaling, and support tumor growth in multiple myeloma and colitis-associated colorectal cancer, as well as contribute to cisplatin resistance through redox adaptation." (PMID 41331166, 2025). "In contrast, cytoplasmic polyadenylation element binding protein 3 (CPEB3) disrupts the crosstalk between colorectal cancer cells and TAMs by targeting the IL-6R/STAT3 signaling pathway, thereby inhibiting EMT." (PMID 40131539, 2025). "Compared to healthy subjects, STAT3 and CXCL8 mRNA expression was increased in neutrophils from colorectal cancer patients, as was STAT3, p-STAT3 and CXCL8 protein expression." (PMID 41019086, 2025). "Niclosamide-induced apoptosis has been reported to occur through the downregulation of STAT3 pathways in colorectal cancer (CRC) cells 9 or the inhibition of NF-kB downstream targets in acute myelogenous leukemia stem cells." (PMID 40657389, 2025). "-Tumor tissues from 7 colorectal cancer patients.-Analysis of IL-11 expression and p-STAT3 activation." (PMID 40650089, 2025). "Convallatoxin inhibits STAT3 phosphorylation in colorectal cancer cells, downregulating the expression of angiogenesis-related genes, including vascular endothelial growth factor (VEGF)." (PMID 40321161, 2025). "TPPP3 modulates STAT3/Twist1 signaling in non-small-cell lung carcinoma and colorectal cancer, promoting proliferation, migration and invasion." (PMID 41148789, 2025). "The research reveals that the Nampt inhibitor FK866 can induce ferroptosis in colorectal cancer cells via the NAD+/Stat3/Gpx4 signaling axis." (PMID 40492508, 2025). "In ulcerative colitis–associated colorectal cancer models, CEBPB overexpression has been tied to increased tumor growth via NF-κB/STAT3 pathway activation." (PMID 41411347, 2025). "Our previous studies demonstrated that acidic environments promote the malignant phenotypes of gastric and colorectal cancer by regulating macrophage-secreted cytokines and influencing the STAT3/c-MYC axis in tumor cells." (PMID 40722682, 2025). "For example, it promotes tumorigenesis in colitis-associated colorectal cancer via the ERK1/2 pathway, and in collagen-induced arthritis, inhibition of the HMGB1/TLR4/STAT3 axis in M1 macrophages alleviates disease severity." (PMID 41009742, 2025). "Oridonin inhibits Wnt/ β- Chain protein signaling pathway, TGF- β The 1/Smads PAI-1 signaling pathway, colon cancer cell metastasis and JAK2/STAT3 signaling pathway to resist colorectal cancer." (PMID 40324265, 2025). "For example, CAF-derived CXCL12 serves as an organotropic factor to mediate the metastasis of CXCR4+ cancer cells, and CAF-derived IL-11 drives colorectal cancer metastasis through STAT3 activation in malignant cells." (PMID 40562870, 2025). "Recently, it has been reported that PDPN(+) CAFs promote angiogenesis in colorectal cancer by activating signal transducer and activator of transcription 3 (STAT3) signaling pathway in ECs." (PMID 39764562, 2025). "Our results showed that PVT1 overexpression is specific for STAT3-mutated T-LGLL, also providing evidence of a STAT3-dependency, similarly to what observed in colorectal cancer, where a STAT3-PVT1 feed-forward regulatory loop was described." (PMID 40721648, 2025).
colorectal cancer (continued). "The binding between c‐Met and B7‐H3 directly activates the c‐Met/STAT3 signaling cascade, promoting cancer cell stemness in both colorectal cancer and glioblastoma‐derived tumor cells." (PMID 40859957, 2025). "TAMs induce EMT to enhance the invasion of colorectal cancer by regulating the JAK2/STAT3/miR-506-3p/FoxQ1 axis." (PMID 40131539, 2025). "Baicalein induces ferroptosis in colorectal cancer cells by the janus kinase 2 (JAK2)/ signal transducer and activator of transcription 3 (STAT3)/ glutathione peroxidase 4 (GPX4) pathway." (PMID 41460836, 2025). "For example, TAMs have been shown to regulate the IL-6/JAK2/STAT3/miR-506-3p/FoxQ1 axis, which enhances colorectal cancer (CRC) motility and invasion through the induction of EMT and upregulation of CCL2, promoting macrophage recruitment." (PMID 40083697, 2025). "In this study, ferroptosis in colorectal cancer cells is induced by FK866 through the NAD+/STAT3/GPX4 pathway." (PMID 40492508, 2025). "More precisely, miR-221/222 have been documented to regulate NF-κB and STAT3 signaling by directly binding to the RelA mRNA coding region, increasing its stability and stimulating colorectal cancer (CRC) development and progression." (PMID 40089465, 2025). "One study in colorectal cancer (CRC) found that the STAT3 protein level was significantly increased despite the unchanged mRNA expression, suggesting the disruption of the normal translational regulation of the STAT3 protein during pathological progression." (PMID 40559853, 2025). "In summary, we propose for the first time that FK866 can induce ferroptosis in colorectal cancer cells through the NAD+ metabolism/Stat3/Gpx4 pathway." (PMID 40492508, 2025). "It was also reported that S100A14 inhibits STAT3-mediated PD-L1 expression, which negatively regulates colorectal cancer stemness and immune evasion." (PMID 39990669, 2025). "Our study provides the first preclinical evidence of BZA as a promising new treatment strategy for colorectal cancer patients where tumour progression is driven by gp130/STAT3 signalling." (PMID 38600086, 2024). "It was found that Th17-type cytokines, IL-6 and TNF-α synergistically activate STAT3 to promote the growth of colorectal cancer cells." (PMID 38710698, 2024). "This work supports the rationale that targeting gp130-dependent STAT3 signalling via the dual inhibition of IL-6 and IL-11 is a novel colorectal cancer treatment opportunity." (PMID 38600086, 2024). "For example, in the process of angiogenesis in colorectal cancer, lncRNAs affect STAT3 by interacting with miRNAs, thereby affecting the migration ability of cancer cells." (PMID 39830506, 2024). "CCL5 contributes to immune suppressive environment, and MΦ‐derived CCL5 facilitates the immune escape of colorectal cancer cells via the STAT3‐PD‐L1 pathway." (PMID 37716915, 2024). "The abnormal expression of LIF in colorectal cancer led to the rapid expansion of tumor cells by activating STAT3 signaling." (PMID 39169307, 2024). "The JAK/STAT3 pathway’s role in mediating the effects of KIF20A highlights its importance in colorectal cancer progression." (PMID 39272816, 2024). "Additional studies have observed that curcumin inhibits IL-6/JAK/STAT3 signaling by significantly reducing the phosphorylation of JAK2 and STAT3 levels in colorectal cancer (CRC) cells." (PMID 38673967, 2024). "A micro-G-protein molecule with GTPase activity in the Ras superfamily, RhoA can activate signal transducer and activator of transcription 3 (STAT3) to promote the formation of various tumors, including breast, gastric cancer and colorectal cancer (CRC)." (PMID 38717722, 2024). "The STAT3 signaling pathway facilitates the accumulation of MDSCs, promoting colorectal cancer growth." (PMID 39100676, 2024).